ADAM9 (ADAM metallopeptidase domain 9)
Diseases named in the same sentence as ADAM9 in open-access papers (continued):
Sharing a sentence is not in itself a finding about the gene and the disease.
cancer (continued). "The first point is to further explore the unknown potential role of ADAM9 in malignant tumors, especially cancer invasion and metastasis." (PMID 32875951, 2020). "And this Naa10p-mediated stabilization of ADAM9 maybe exist in other cancer types to drive tumorigenesis as well." (PMID 33096780, 2020). "Additionally, ADAM9 is also found to contribute to the angiogenesis and vascular remodeling of cancer cells." (PMID 33146718, 2020). "The roles of ADAM9 in different types of cancers have been discussed in many previous works." (PMID 31793719, 2020). "ADAM9 and CDCP1 are oncogenic membrane proteins that have been linked to cancer metastasis." (PMID 28537886, 2017). "All these previous reports above suggested that ADAM9 may potentially play an important role in cancer invasion and metastasis." (PMID 27571068, 2016). "Overexpression of ADAM9 has been observed in many cancers and is correlated with brain metastasis." (PMID 24705471, 2014). "Since elevated ADAM9 expression is observed in many advanced tumors, this raises the possibility that ADAM9 might be a potential biomarker for cancer targeted gene therapy, although more research is necessary." (PMID 23342005, 2013). "Knockdown of ADAM9 expression enhanced the sensitivity of cancer cells to radiation." (PMID 23342005, 2013). "In NSCLC cell lines, ADAM9 overexpression in A549 cells was shown to increase the ability of adhesion, invasion and metastasis to the brain tissue of nude mice, through modulation of integrin α3β1 function in cancer cells." (PMID 23761811, 2013). "ADAMs shown to play a role in cancer include ADAM9, ADAM10, ADAM12, ADAM15 and ADAM17." (PMID 21906355, 2011). "Moreover, ADAM9 promotes cancer cell invasion by modifying or regulating e-cadherin and several types of integrins." (PMID 18582378, 2008). "Notably, enhanced expression levels of ADAM9-S have been detected in human PCa serum 42, suggesting that ADAM9 may be a predictive biomarker of cancer progression in PCa clinical and serum specimens." (PMID 36778124, 2023). "Two different approaches could be used to inhibit ADAM9 in cancer treatment." (PMID 32683508, 2021). "Moreover, ADAM9 is not only enriched in PDAC but seems to be overexpressed in several cancer types; consequently, we hypothesized that our ADAM9-responsive delivery system may be used outside of PDAC." (PMID 34282781, 2021). "However, whether and how the interaction of ADAM9 with these transcription factors regulate other genes or pathways during cancer progression need to be clarified in future studies." (PMID 34671207, 2021). "To validate this hypothesis, we assessed ADAM9 levels in a large set of cancer cell lines." (PMID 34282781, 2021). "Therefore, targeting ADAM9 might provide a new route of treating inflammatory diseases as well as cancer." (PMID 33096780, 2020). "Moreover, miR-126 inhibits the metastasis of prostrate cancer cell through targeting ADAM9." (PMID 33146718, 2020). "In addition, it has also been indicated that ADAM9 might potentially contribute to the pathogenesis of human cancers, and can potentially be a good therapeutic target for developing anti-cancer drugs." (PMID 27571068, 2016). "Furthermore, we found that miR-126-3p regulates the expression of many cancer-related genes, including those encoding solute carrier family 7 member 5 (SLC7A5) and a disintegrin and metalloproteinase domain-containing protein 9 (ADAM9), and that it directly targets these genes." (PMID 26244545, 2015). "Additionally, HMGB1 (High-Mobility Group Box 1) and ADAM9 (A Disintegrin and Metalloproteinase 9) are upregulated in PC and verified as targets for miR-129-5p across digestive malignancies implying more extensive anti-cancer actions and pending additional functional studies in PDAC70,71." (PMID 40730640, 2025).
cancer (continued). "Immunohistochemical results showed various staining intensities, ranging from weak to intense, of ADAM9, CDCP1, and t-PA expressions in the cytoplasm or at the cell membrane of most cancer cells within the cancer cell nests of OSCC specimens." (PMID 39441449, 2024). "MiR-126 alters the biological functions of some genes such as PI3K, EGFL7, HOXA9, sKRAS, CRK, ADAM9, IRS-1, SOX-2, SLC7A5, and VEGF, as well as involves in inflammation, cell migration, angiogenesis, recurrence of cancer, and metastasis." (PMID 38445462, 2024). "ADAM9 was observed to be highly expressed in CHOL, whereas ADAM33 had a significantly lower expression in pan-cancers, especially in BLCA and UCEC." (PMID 37082201, 2023). "The oncogene ADAM Metallopeptidase Domain 9 (ADAM9) and lncRNA HULC are also modulated by miR-203 to block the invasion and migration of cancer cells via targeting ATP Binding Cassette Subfamily E Member 1 (ABCE1) factor." (PMID 36016398, 2022). "Fisetin can continue to phosphorylate ERK1/2 and reduce the expression levels of ADAM9 protein and mRNA through the ERK1/2 pathway, thereby effectively inhibiting the migration and invasion of related cancer cells." (PMID 32875951, 2020). "MiR-203 is a cancer suppressor that interacts with different genes involved in hepatocarcinogenesis, such as EZH2 and BMI1, SURVIVIN, RASAL2, ADAM9, and MMP2." (PMID 31073374, 2019). "Both ADAM9 and SLC7A5 play important roles in several cancers and have been shown to be targeted by miR-126-3p." (PMID 26244545, 2015). "We also found that miR-126-3p targets genes involved in cancer, and directly regulates SLC7A5 and ADAM9 expression." (PMID 26244545, 2015). "Such “onco-miRNAs” have also been demonstrated in PDAC: miR-196a promotes cancer progression by targeting NFKBIA, and miRNA-126 and 148a inhibit cancer cell growth by down-regulating CDC25B and ADAM9, respectively." (PMID 25742499, 2015). "ADAM9 is reportedly involved in several human diseases such as inflammatory disorders, oxygen-induced retinopathy (OIR), and cancer." (PMID 25177692, 2014). "Beside a number of functions, ADAM9 and MMP7 share the proteolytic cleavage of HB-EGF, whose expression results significantly increased in many human cancers." (PMID 23437250, 2013). "The overexpression of ADAM8, ADAM9, ADAM10, ADAM12, ADAM15, ADAM17, and ADAM28 are reported from various cancers." (PMID 22272227, 2012). "ADAM9 expression status was confirmed with RT-PCR at 72 h in only control cancer cell lines, not ADAM9 knockdown cancer cell lines." (PMID 35740916, 2022). "Notably, ADAM9 is acknowledged as a putative therapeutic target in HCC owing to its role in the immune microenvironment and cancer development." (PMID 32683508, 2021). "Fisetin (3,3′,4′,7-tetrahydroxyfavone), a naturally occurring flavonoid commonly found in plants is effective against cancer, and its possible mechanisms includes suppression of proliferation and metastasis of RCC through upregulation of MEK/ERK-Targeting CTSS and ADAM9." (PMID 32760434, 2020). "Our approach covers a broad spectrum of cancer biology, of which LAMC2, ANXA2, ADAM9, and APLP2 are the most important features of the tested diagnostic model, and their implementation in clinical settings could be further examined." (PMID 30700038, 2019). "The roles of LAMC2, ANXA2, ADAM9, and APLP2 in cancer biology have been documented." (PMID 30700038, 2019). "Next, to determine the function of ADAM9 in vascular remodeling, we measured the level of secreted VEGFA in conditioned media of cancer cells by ELISA and found lower concentrations of VEGFA in ADAM9 knockdown cell media compared to that in control (shGFP) cell media." (PMID 29118335, 2017). "ADAM9 is also responsible for mediating EGF receptor activity and is capable of regulating E-cadherin and integrins, demonstrating its important role in cancer cell invasion, migration and metastasis." (PMID 23761811, 2013).
cancer (continued). "On the basis of putative cancer-related annotations, two genes, namely ADAM metallopeptidase domain 9 (ADAM9) and maltase-glucoamylase alpha-glucosidase (MGAM), that mapped to CNA regions were selected for further evaluation of their mRNA expression using reverse transcriptase qPCR." (PMID 23405089, 2013). "It is interesting to note that none of the normal tissues and only two of the cancer cases were completely negative for ADAM9." (PMID 18582378, 2008). "In contrast to a cancer-promoting role of exosomal miRNAs, a recent pancreatic cancer study found that exosomes derived from bone marrow mesenchymal stem cell (BMSC) contain elevated levels of miR-126-3p, which subsequently downregulate ADAM9 and suppress cancer progression." (PMID 34204940, 2021). "Hence, the clinical success for targeting ADAM9, they should need to be highly selective and able to accumulate in cancer tissues without eliciting systemic toxic effects." (PMID 32719332, 2020). "Finally, we like to add some information on ADAM9 to this synopsis of pathways as this factor has recently emerged to play a significant role in a multitude of pathways regulating EMT and promoting metastasis in various cancers." (PMID 31641356, 2019). "However, the remaining eight cancer-specific DESPGs of GLB1, HSPA5, PDIA3, GNRH1, IFNGR2 ADAM9, TPST2, and TAC4) were not reported in any researches, which could be potential novel prognostic biomarkers in corresponding tumors." (PMID 31824949, 2019).
infection (15 papers, 2011 to 2025). The state of being infected such as from the introduction of a foreign agent such as serum, vaccine, antigenic substance or organism. "Transduction of HAP1 ADAM9KO cells with mADAM9-E348A and subsequent infection of several clones with EMCV showed that mADAM9-E348A overexpression increases the susceptibility of human ADAM9-deficient cells to EMCV." (PMID 31409686, 2019). "WT and ADAM9 knockout cells were equally susceptible to infection with CVB3, VSV, IAV, and HSV-1." (PMID 30723129, 2019). "Using this strategy, they found that both wild-type and ADAM9-deficient cells could support high levels of infection." (PMID 30914507, 2019). "In contrast, cardiac tissue from Adam9 KO mice showed diffuse, widespread infection with high levels of EMCV RNA genomes detected throughout all regions of the heart." (PMID 38755212, 2024). "The levels of MIP-1α, MIP-1β, IL-6, RANTES, MCP-1, and CXCL1 were significantly reduced in Adam9 KO compared to WT mice after infection." (PMID 38755212, 2024). "Immunohistochemistry confirmed structural damage with corresponding troponin leakage in the hearts of Adam9 KO mice following EMCV infection." (PMID 38755212, 2024). "ADAM9 was identified as a potential host factor for SARS-CoV-2 S-protein-mediated infection as ADAM9 knockdown resulted in significantly diminished SARS-CoV-2 infection." (PMID 39205219, 2024). "The abolishment of ADAM9-enhanced Vpp infection by these inhibitors suggests that ADAM9-mediated viral entry requires endosomal acidification." (PMID 37713503, 2023). "Our data showed that silencing ADAM9 reduced virus entry, while its overexpression promoted infection." (PMID 37713503, 2023). "In contrast, pretreatment of NH4Cl and BafA1 in ADAM9-transfected cells decreased Vpp infection to comparable levels with mock-transfected cells." (PMID 37713503, 2023). "Upon SARS-CoV-2 Spike Vpp infection, the ADAM9 KD H1650 cells significantly diminished virus infectivity to 59% and 52%." (PMID 37713503, 2023). "Nonetheless, significant inhibition of Vpp infection by ADAM9 knockdown was observed across the alpha, delta, and omicron variants." (PMID 37713503, 2023). "Mechanistic studies in infection highlight the relevance of ADAM9 during viral infection from pathogen entrance to systemic changes." (PMID 33392273, 2020). "ADAM10 and ADAM17 together with ADAM8 and ADAM9 seem to be the most relevant ADAM proteases in infection; however, some studies point toward an additional influence of ADAM12, ADAM15, and ADAM33." (PMID 33392273, 2020). "This study demonstrates that ADAM9 functions as a major EDF involved in the early infection of both human and murine cells." (PMID 30723129, 2019). "Together, these data pointed to a role of ADAM9 in an early step in infection, such as viral entry or genome translation." (PMID 31409686, 2019). "Given that different strains of EMCV have differential binding activities to attachment factors, such as sialic acid, they tested the role of ADAM9 during infection by a second strain of EMCV." (PMID 30914507, 2019). "Therefore, these cells are not suitable for analyzing antiviral innate responses to EMCV because the failure of Adam9 KO LFs to produce IFN-β following authentic EMCV infection likely reflects the failure of live EMCV to enter and replicate in these cells." (PMID 38755212, 2024). "Furthermore, we found enhanced co-localization between ACE2 and ADAM9 upon SARS-CoV-2 Spike Vpp infection." (PMID 37713503, 2023). "Thus, it seems feasible that ADAM9 is not only involved in the acute phase of infection but also in the decision between resolution of inflammation, chronicity, and systemic changes." (PMID 33392273, 2020). "EMCV may directly bind to ADAM9, but we and others have observed polysaccharide-related binding that may facilitate productive infection." (PMID 30723129, 2019). "Mouse ADAM9 supports EMCV infection independently of its metalloprotease activity." (PMID 31409686, 2019).
infection (continued). "In contrast, ADAM9 KO and WT cells were equally susceptible to infection with other viruses, including the picornavirus Coxsackie virus B. ADAM9 KO cells failed to produce viral progeny when incubated with EMCV." (PMID 30723129, 2019). "Furthermore, we showed that the dependency on ADAM9 for infection is unique to EMCV, as infection with other RNA and DNA viruses was not affected by ADAM9 deficiency." (PMID 30723129, 2019). "Since the extracellular domain but not the enzymatic activity or intracellular domain is required for infection, the data suggest that ADAM9 acts as an entry receptor or at an early step in the process, shedding light on the biology of EMCV infection and pathogenesis." (PMID 30914507, 2019). "Next, to establish whether ADAM9 expressed on the cell surface is required for EMCV infection, we neutralized infection with an ADAM9-specific antibody." (PMID 31409686, 2019). "However, little is known about the activities of ADAM9 in regulating physiologic or pathologic processes, especially during acute infection or in response to tissue damage." (PMID 27990250, 2015). "Thus, we investigated whether the infection of SARS-CoV-2 B.1.1.7 (alpha), B.1.617.2 (delta), and B.1.1.529 (omicron) variants would be reduced in ADAM9 KD H1650 cells." (PMID 37713503, 2023). "Our data demonstrated that ADAM9 is essential for IFN-β induction during EMCV and CVB3 infection in vivo and to EMCV vRNA challenge in vitro, but ADAM9 was not required for the IFN response to RIG-I ligands." (PMID 38755212, 2024). "Here, we identified a disintegrin and metalloproteinase domain 9 (ADAM9), a member of the ADAM family of type I transmembrane proteins, as a host factor in SARS-CoV-2 Spike-mediated infection." (PMID 37713503, 2023). "Thus ADAM9 blood transcript levels, or possibly levels of circulating proteins, could potentially be employed for triage of patients presenting with symptoms of infection in the emergency room or for monitoring of patients in intensive care units." (PMID 27990250, 2015). "When fibroblast cells were transfected with low amounts of vRNA, we observed a reduced yield of viral progeny from Adam9 KO compared to WT, likely reflecting the spread of infection to bystander fibroblasts in cultures of WT, but not Adam9 KO, cells." (PMID 38755212, 2024). "We found that SH3BP4, ADAM9, and TMEM2 display enhanced binding to CoV2-RBD compared to CoV-RBD, suggesting that specific amino acid changes in CoV2-RBD enable SARS-CoV-2 to bind these host factors thereby potentially promoting infection." (PMID 38777146, 2024). "Similarly, the efficient ADAM9 RNA reduction in stable ADAM9 KD HEK293T cells (44% and 34%) markedly decreased SARS-CoV-2 Spike Vpp infection to 46% and 62%." (PMID 37713503, 2023). "They found that ADAM9 was required for infection by both strains of EMCV but not another picornavirus, Coxsackie virus B3, or unrelated viruses, suggesting specificity." (PMID 30914507, 2019). "Preincubation of EMCV with soluble ADAM9 protein (up to 50 μg/ml) inhibited infection of HAP1 cells, without having adverse effects on CV-B3 infection or cell morphology." (PMID 31409686, 2019). "This suggests that protease activity is dispensable for infection and that ADAM9 did not indirectly control infection through the cleavage of another host factor." (PMID 30914507, 2019). "In the absence of these inhibitors, ADAM9-transfected cells increased Vpp infection." (PMID 37713503, 2023). "The largest reduction in infection efficiency was observed in cells lacking ADAM9." (PMID 31409686, 2019). "Batimastat barely inhibited infection of HAP1 cells by Renilla luciferase-expressing EMCV and CV-B3 at concentrations up to 200 μM, which is a concentration 4,000-fold higher than the 50% inhibitory concentration (IC50) value reported for ADAM9 inhibition in cell-based assays." (PMID 31409686, 2019).
infection (continued). "In addition we observed that the abundance of ADAM9 was increased during acute infection but did not change after stimulation with pathogen-derived molecules." (PMID 27990250, 2015). "Knockout of ADAM9 strongly inhibited infection of different EMCV strains in both human and mouse cells, and this inhibition could be bypassed by transfection-mediated delivery of viral RNA to the cytosol, supporting the idea that ADAM9 is required for virus entry." (PMID 31409686, 2019). "Analysis of luciferase reporter expression in the absence of GPC-N114 at 6 h postinfection (i.e., within a single replication cycle) showed that knockout of ADAM9 and PTPN11, but not FGFR1, significantly inhibited EMCV infection." (PMID 31409686, 2019). "Antibody pretreatment inhibited infection of HAP1 cells with EMCV, but not with CV-B3, indicating that the support of EMCV infection by endogenous ADAM9 takes place at the cell surface or in the endocytic compartment." (PMID 31409686, 2019). "Furthermore, ADAM9 wild type (ADAM9-WT) significantly increased SARS-CoV-2 Spike Vpp infection but not VSV-G, whereas a catalytically inactive ADAM9-E348A mutant did not affect both SARS-CoV-2 Spike and VSV-G Vpp infection compared with mock." (PMID 37713503, 2023).
breast (4 papers, 2019 to 2022). "Next, the role of ADAM9 in acute alcoholic liver injury in vitro in cultured mouse cells and in vivo in a hydrodynamic injection-based alcoholic liver injury mouse model was documented." (PMID 35707386, 2022).
degenerative diseases (3 papers, 2020 to 2025). "Altogether, ADAM9 is expressed broadly in human tissues, and participates in the development, inflammatory processes, and degenerative diseases." (PMID 33096780, 2020). "In physiological conditions, ADAM9 expresses broadly in the body, but it is also involved in various pathophysiological conditions, including inflammation and degenerative diseases." (PMID 33096780, 2020). "ADAM9 influences the developmental process, inflammation, and degenerative diseases." (PMID 33096780, 2020).
adenocarcinoma (2 papers, 2014 to 2019). A common cancer characterized by the presence of malignant glandular cells. "In this study, the positive ratio of ADAM9 was 87% (29 out of 33 cases) and 78% (11 out of 14 cases) in squamous cell- and adenocarcinoma, respectively, which are values that are somewhat lower than the 93% (13 out of 14 cases) given in the previous report." (PMID 25177692, 2014).